AQP4 (aquaporin 4)
Diseases named in the same sentence as AQP4 in open-access papers (continued):
Sharing a sentence is not in itself a finding about the gene and the disease.
Cognitive impairment (continued). "Moreover, the stimulator critically modulates AQP4 polarization, which is essential for enhancing glymphatic clearance, thus improving brain recovery from ischemic damage and potentially reducing neurological, motor, and cognitive deficits." (PMID 39927473, 2025). "However, the AQP4 level did not remain independently associated with cognitive impairment in the binary logistic regression analysis." (PMID 35111362, 2022). "Indeed, studies performed in AD and CAA transgenic mouse models have confirmed that AQP4 deletion promotes cognitive deficits and increases Aβ accumulation and synaptic damage, suggesting a possible contribution of AQP4 to Aβ clearance through the brain vasculature." (PMID 33801197, 2021). "Overall, 10 (55%) MOGAD, 23 (66%) AQP4+NMOSD, 9 (60%) dsNMOSD patients, and 7 (28%) HC showed cognitive impairment." (PMID 41493508, 2026). "AQP4 is upregulated in the peripheral blood of SAE patients and in the brain tissue of a mouse model in which AQP4 deletion can reduce cognitive impairment by activating astrocytic autophagy and inhibiting neuroinflammation." (PMID 39544938, 2024). "The therapeutic modulation of this system, through agents such as the AQP4 inhibitor TGN-020, suggests a promising avenue for enhancing neurological recovery and reducing cognitive deficits." (PMID 38253938, 2024). "However, further research is needed to clarify whether the reduction in cognitive impairment due to AST-120 is a direct result of changes in hippocampal aquaporin-4 and glial fibrillary acidic protein levels or a secondary effect of decreased uremic toxin levels." (PMID 39595807, 2024). "Aquaporins, particularly AQP4, also play a significant role in the pathophysiology of SAE, characterized by vasogenic cerebral edema and cognitive impairment." (PMID 39768394, 2024). "Collectively, these findings position AQP4 as a critical mediator in SAE pathogenesis, presenting it as a potential therapeutic target to alleviate brain edema and cognitive impairment in sepsis." (PMID 39768394, 2024). "In clinical practice, we also observed cognitive impairment of NMOSD, and the serum AQP-4 antibody titer of patients gradually decreased with disease remission." (PMID 36672071, 2023). "Then, we analyzed the data of AD mice and patients with cognitive impairment in the public database and found that our data were consistent with the results of the public database analysis, which verified our hypothesis that the polarization distribution of Aqp4 is obvious in AD." (PMID 36819717, 2023). "Diffusion of AQP4-abs within the underlying cortex could then be the pathological driver of the loss of AQP4 reactivity in cortical layer I, and the associated neuronal loss in cortical layers II–IV observed in NMOSD patients with cognitive impairment [87▪▪,91]." (PMID 29465432, 2018). "β-Asarone improved cognitive impairment, alleviated Aβ deposition and hippocampal damage, and inhibited GFAP, AQP4, IL-1β, and TNF-α expression." (PMID 29599803, 2017). "Although previous studies reported increased IL-6 CSF levels in NMOSD patients and some associations with more severe clinical and cognitive deficits, we did not observe differences in IL-6 levels between NMOSD AQP4 + patients, RRMS patients, and NIC." (PMID 41057549, 2025). "Elevated ammonia levels in SAE, due to non-hepatic hyperammonemia, contribute to increased AQP4 expression in astrocytes, leading to cognitive impairment." (PMID 39544938, 2024). "As our results, AQP4 knockout did not induce cognitive impairment in normal mice, it suggests that AQP4 is not pivotal in physiological condition, but in the SAE pathological condition." (PMID 36922751, 2023). "Evidence from a series of recent experiments revealed that AQP-4 is responsible for bulk ISF flow in the glymphatic system, and its deletion resulted in Aβ deposition, aggravation of cognitive impairment, and induction of cerebral amyloid angiopathy in APP/PS1 mice." (PMID 36551947, 2022).
Cognitive impairment (continued). "Another experimental study reported that in Aβ42-induced rats, β-asarone improved cognitive impairment and alleviated Aβ deposition by protecting astrocytes, which was possibly achieved by reducing the levels of TNF-α and IL-1β and then downregulating AQP4 expression." (PMID 35215287, 2022). "In animal experiments, the lack of AQP4 in APP/PS1 mice (AD model) led to an increase in Aβ aggregation and the loss of synaptic proteins, which aggravated cognitive impairment." (PMID 35111362, 2022). "A recent study analyzed AQP4 expression in the circulation of CAA patients with intracerebral hemorrhage and demonstrated that lower circulating levels of AQP4 were related to ApoE ε4 carriers, cognitive impairment and previous hemorrhagic stroke." (PMID 35111362, 2022). "Despite the varied findings all groups have concluded that the lack of AQP4 results in cognitive deficits and these data have shed some light into the possible role of AQP4 in regulating learning and memory." (PMID 26941623, 2016). "Likewise, in this study of AD patients, it was observed that in the frontal cortical gray matter, the perivascular localization of AQP4 was significantly reduced compared to that in subjects without cognitive impairment." (PMID 38334678, 2024). "Potential mechanisms of cognitive impairment in NMOSD are speculated to be related to brain lesions and serum AQP-4-IgG positivity, while the evidence of potential correlation between serum AQP-4-IgG and cognitive impairment is lacking." (PMID 36672071, 2023). "Therefore, AQP-4 may be essential for cognitive impairment following systemic inflammation, which has not been investigated until now." (PMID 39534317, 2024). "Although our MOGAD patients showed lower cerebral MRI lesion load than AQP4+NMOSD and dsNMOSD, lesion load alone does not consistently predict cognitive impairment in NMOSD, while only limited data is available for MOGAD." (PMID 41493508, 2026). "Furthermore, the Aqp4 knockout APP/PS1 mice had more severe deficits in glymphatic transport functions, Aβ plaque deposition, and cognitive impairment, which were not alleviated after the exercise intervention." (PMID 38430054, 2024).
edema (64 papers, 2007 to 2025). An abnormal accumulation of fluid beneath the skin, or in one or more cavities of the body. "The primary isoform of AQP4 expressed on astrocytes and ependymal cells has been linked to cerebral edema brought on by traumatic brain injury." (PMID 38872838, 2024). "In a study, Aqp-4 knockout mice have been shown to survive much better than wild-type mice in a model of brain edema caused by acute water intoxication." (PMID 37533514, 2022). "The importance of aquaporin-4 in the development of cerebral edema was confirmed by studies on the sepsis-associated encephalopathy model, which showed that a higher level of aquaporin-4 was directly associated with a more severe degree of edema." (PMID 35627746, 2022). "For instance, in focal and global cerebral ischemia models, AQP4 knockout mice showed reduced cerebral edema, infarct volume, intracranial pressure and neuronal loss vs control mice." (PMID 35177771, 2022). "As the degree of brain edema is associated with the clinical indications after ischemia-reperfusion injury, the brain water content, and the expression of aquaporin-4 (AQP-4) were also detected." (PMID 33643044, 2021). "Brain edema is considered a leading cause of eclamptic seizures; aquaporins (AQP4 and AQP9), the glial water channel proteins mainly expressed in the nervous system, play an important role in brain edema." (PMID 29351212, 2018). "In the freeze-injury model of vasogenic brain edema, AQP4-deficient mice had the worst clinical outcome." (PMID 23516588, 2013). "Upregulation of AQP4 is implicated in the formation and resolution of cerebral edema after DAI under acute alcohol intoxication." (PMID 24282821, 2013). "The traumatic brain edema and associated glymphatic tracer detention induced by hypothermia might be related to a loss of perivascular AQP4 expression." (PMID 36341130, 2022). "Activity of AQP4, the predominant aquaporin in the brain, has been implicated in brain edema." (PMID 24282821, 2013). "In contrast, in a vasogenic edema induced by brain tumor and persistent ischemia, AQP-4 helps with the clearance of vasogenic cerebral edema fluid due to BBB leakage." (PMID 37504937, 2023). "In general, there are controversies in the literature concerning the protective or detrimental effect of AQP4 deletion in different pathologies where brain edema occurs." (PMID 36568889, 2022). "It has been shown that this calmodulin-inhibiting antipsychotic drug repressed AQP4 localization to the blood-spinal cord barrier, ablated AQP4-mediated cerebral edema, and led to accelerated functional recovery in rats." (PMID 35563385, 2022). "In particular, aquaporin-4 (AQP4), expressed in astrocytes, is known to be involved in the pathogenesis of brain edema and has attracted attention as a therapeutic target." (PMID 34638890, 2021). "Previous results showed that the water permeability of astrocytes was significantly decreased after the knockout of AQP4 and reduced the occurrence of cerebral edema." (PMID 33013433, 2020). "In pathophysiologic conditions, i.e., in the ischemic brain edema, AQP4 is shown to internalize and colocalize with early ensodome marker EEA1, as was demonstrated in rat brain sections." (PMID 32192013, 2020). "Because AQP4 expression in astrocytes was shown to be induced by hyperosmotic mannitol solution, which is commonly used to reduce brain edema, it has been suggested that AQP4 plays an important role in the treatment of brain edema." (PMID 31039748, 2019). "Although NMDAR and AQP4 are important factors for the occurrence and development of brain traumatic edema, their interactions are poorly understood." (PMID 30483388, 2018). "AQP4-null mice studies suggest that AQP4 plays a double and contradictory role in post-ischemic brain edema indulging cytotoxic edema and eliminating vasogenic edema-derived accumulation of cerebral fluid into parenchyma." (PMID 30513991, 2018).
edema (continued). "Numerous studies report a crucial role of AQP4 in development and resolution of brain edema of any origin, e.g., of ischemic, hemorrhagic, infectious, and traumatic one." (PMID 30333785, 2018). "As learned from the AQP4 knockout animal experiments, the molecular response by AQP4 expression in posttraumatic brain edema depends on the predominant edema form (vasogenic vs. cytotoxic) and this rule is to be extrapolated into traumatic brain injury models." (PMID 30333785, 2018). "We have recently reported that in rats, hypoxia-induced overactivation of CRHR1 and AQP4 produces cerebral edema tested by magnetic resonance imaging (MRI)." (PMID 26968975, 2016). "It has been observed that, in the early phase of cytotoxic edema, AQP4 facilitated edema fluid formation, while the rate of edema fluid elimination was increased by AQP4 in vasogenic brain edema." (PMID 26346093, 2015). "In summary, administering ectogenic PROG attenuates BBB damage and cerebral edema in HIBD neonatal rats by downregulating the expression of AQP-4 and MMP-9 in the brain cortex." (PMID 23935758, 2013). "Early in cytotoxic edema, AQP4 facilitates edema fluid formation, but in vasogenic brain edema, AQP4 increases the rate of edema fluid elimination." (PMID 24282821, 2013). "Investigating the effect of HS on up-regulation of brain AQP4 during LPS-induced mice brain edema would provide clues to reveal the mechanism of HS down-regulation of brain AQP4 in bacterial meningitis." (PMID 23036239, 2012). "In another model of brain edema, focal ischemic stroke produced by MACO, AQP4-deficient mice have improved neurological output." (PMID 20815926, 2010). "An unexpected role for AQP4 in vasogenic brain edema was shown using three models of vasogenic brain edema in mice." (PMID 17347837, 2007). "Inhibition of AQP4, regulation of inflammation and suppression of immune response may be the three treatment methods for cerebral edema after TBI." (PMID 37213674, 2023). "These provides evidence for early intervention of AQP4 to reduce brain edema." (PMID 37213674, 2023). "In the light of this data on relationship between AQP4 function and form of brain edema, a certain mismatch in our set of results needs to be admitted: The previous description of CHI model, as well as our own radiological results suggests that cytotoxic edema prevails in our experimental setting." (PMID 30333785, 2018). "Since curcumin reduced also acute IL-1β expression in pericontusional astrocytes and attenuated IL-1β-induced AQP4 expression in cultured astrocytes, the authors suggested that IL-1β may promote cerebral edema via the regulation of AQP4." (PMID 26346093, 2015). "The alcohol-mediated inhibition of AQP4 could aggravate vasogenic brain edema by blocking fluid clearance following vasogenic brain edema that follows mechanical injury with DAI under acute alcohol intoxication." (PMID 24282821, 2013). "Our results show acute alcoholism may inhibit the expression of AQP4, thus, alleviating cytotoxic cerebral edema at early stages of DAI under acute alcohol intoxication." (PMID 24282821, 2013). "Spatial co-localization of aquaporin water channels (AQP4) and inwardly rectifying potassium ion channels (Kir4.1) on the endfeet regions of glial cells has been suggested as the basis of functionally interrelated mechanisms of osmoregulation in brain edema." (PMID 20806048, 2010). "Therefore, AQP4 inhibitors are expected to protect the brain in cytotoxic edema, whereas AQP4 activators or upregulators would be required to facilitate the clearance of vasogenic brain edema." (PMID 17347837, 2007). "Therefore, we came to the first conclusion that the expression of miR-7-5p decreased after ICH; as a result, the inhibition of the PI3K/AKT pathway was weakened, and the activation of the PI3K/AKT pathway resulted in an increase in AQP4 expression and AQP4-aggravated brain edema." (PMID 33392188, 2020).
edema (continued). "Also, the expression of aquaporin-4 is correlated with peritumoral brain edema." (PMID 23877362, 2013). "Moreover, increased extracellular water transport and accumulation was present in inner retina, which is characterized by increased extracellular fluid volume, increased aquaporin-4 (AQP-4) immunoreactivity and swelling of retinal glial cells, leading to inner retinal edema." (PMID 22053184, 2011). "Aquaporin 4 is the major water channel in the brain, expressed predominantly in astroglial cells, and plays a major role in fluid clearance in vasogenic brain edema, whereas podoplanin is a lymphatic endothelial cell marker and has been reported to be upregulated in astrocytic tumors." (PMID 18021406, 2007). "Activated microglia produce IL-6, which enhances astrocytic expression of aquaporin-4 (AQP4) and ultimately contributes to posttraumatic brain edema." (PMID 40661949, 2025). "Aquaporin 4 (AQP4) is highly expressed in astrocytes and involved in the development of brain edema following intracerebral hemorrhage." (PMID 34867389, 2021). "A study on brain edema secondary to brain trauma found that the phosphorylation of AKT can affect the phosphorylation of Foxo3a and thus affect the expression of AQP4." (PMID 33392188, 2020). "Aquaporin 4 (AQP4), the major AQP in the brain, mediates free transmembrane transport of water molecules, as evidenced by decreased expression in vasogenic cerebral edema (BBB incomplete)." (PMID 36820986, 2023). "In the intracranial hemorrhage (ICH) model, CBL can ameliorate secondary injury and promote behavioral performance during the acute phase by reducing brain edema, the inflammatory response, and BBB permeability by decreasing the expression levels of IL-1β, TNF-a, IL-6, and AQP4." (PMID 36074398, 2022). "Thus, minocycline mediated cerebral edema and BBB disruption via the two distinct mechanisms: inhibitory effect on AQP4 and optimizing function of AQP4 localization." (PMID 34975343, 2022). "AQP1, AQP4 and AQP9 have been clearly identified as brain-specific; among them, AQP4 is the most important family member that has been well described as participating in brain edema and other various brain diseases." (PMID 28423683, 2017). "Continued AQP4 expression even after BBB disruption may exacerbate subsequent brain edema, as suggested by another study demonstrating that development of brain edema was greatly attenuated in AQP4 knock-out mice." (PMID 21119881, 2010). "However, it is important to note that WT mice showed better survival and functional outcomes after a brain edema in comparison to mouse models lacking aquaporin-4 (AQP4), a water transport system that allows for bidirectional water flux." (PMID 33513812, 2021). "Since the absence of AQP4 causes the significant difference, combined with our previous study, we speculate that AQP4 may play an important role in VEGF’s effect on brain edema after ICH." (PMID 23805198, 2013). "Notably, in the animal model of minor head injury, where brain edema is of lesser relevance for the posttraumatic course, lack of AQP4 was demonstrated to be neuroprotective (an effect similar to pathophysiological conditions with cerebral edema of cytotoxic type)." (PMID 34966347, 2021). "Although there has not been much research on the regulation of AQP-4 directly related to BBB physiology so far, its role in the pathogenesis of cerebral edema along with BBB dysfunction and disruption has been examined by multiple mouse models." (PMID 37504937, 2023).